MTOR (mechanistic target of rapamycin kinase)
Diseases named in the same sentence as MTOR in open-access papers (continued):
Sharing a sentence is not in itself a finding about the gene and the disease.
breast cancer (continued). "Collectively, these data provide strong evidence that mTOR inhibition induces breast cancer cell plasticity and stemness in vivo." (PMID 32427827, 2020). "It has been shown that activated mTOR leads to increased tumor progression and decreased patient survival, with mTOR activation being more common in TN breast cancer." (PMID 32012648, 2020). "In recent studies, miR-489-3p was shown to interact with the PI3K/AKT/mTOR signaling in various cancers, such as glioma, breast cancer, and melanoma." (PMID 33193658, 2020). "In vitro results show that DHW-208 is a dual inhibitor of PI3K and mTOR, and suppress the growth of human breast cancer cells by targeting the PI3K/AKT/mTOR pathway." (PMID 32606352, 2020). "EVE is an mTOR inhibitor that has emerged as an effective drug in the management of malignancies, such as breast cancer, renal cell carcinoma, subependymal giant cell astrocytoma, and neuroendocrine tumors." (PMID 32668776, 2020). "This knowledge would advance our understanding of the mechanism of how energy imbalance affects breast cancer prognosis and shed light on the potential for promoting energy balance and mTOR inhibition as strategies to improve clinical outcomes." (PMID 33024820, 2020). "It is becoming clear that resistance mechanisms to kinase inhibitors in breast cancer often involve PI3K/AKT/mTOR pathway hyperactivation." (PMID 32226926, 2020). "The PI3K/AKT/mTOR and Wnt/β-catenin signaling pathway play important roles in proliferation and survival of breast cancer." (PMID 32501811, 2020). "Through suppression of PTEN expression, microRNA‐221 activates Akt/mTOR signaling and leads to adriamycin insensitivity of breast cancers." (PMID 31899608, 2020). "Our observation confirms PRR14’s overexpression and its effect on activating the PI3K/AKT/mTOR signaling pathway in breast cancer." (PMID 32541902, 2020). "RY10-4, an analog version of proto-apigenone, promotes ACD by inactivation of the AKT/mTOR pathway in the breast cancer cell line MCF-7, and the inhibition of autophagy through genetic and chemical approaches extends cancer cell viability." (PMID 33194736, 2020). "Everolimus is one of the main drugs that targets mTOR, and numerous studies have demonstrated its effectiveness in breast cancer therapy." (PMID 32211045, 2020). "The mTOR inhibitor everolimus is a possible alternative treatment for breast cancer resistant to AIs." (PMID 32099680, 2020). "The mTOR inhibitor everolimus was shown to increase the effectiveness of paclitaxel in treating TN breast cancers in clinical trials." (PMID 32012648, 2020). "Similar to our data, it was shown that MCF-7 breast cancer cells treated with metformin and rapamycin, two known mTOR inhibitors, had decreased levels of both total-mTOR and phosphorylated/activated mTOR." (PMID 32012648, 2020). "This is achieved by the activation of different pathways including mTOR and NF-KB signaling in the breast cancer cells." (PMID 32092997, 2020). "Rapa treated cells showed high intensity of TG(16:0/18:1/18:1) isotopomers, which indicated the TG storage was suppressed by mTOR expression in MCF-7 breast cancer cells." (PMID 32751454, 2020). "Collectively, these models demonstrate ISRIB’s potential to attenuate the breast cancer plasticity induced by stimuli including hypoxia, mTOR inhibitors, and paclitaxel." (PMID 32427827, 2020). "PI3K, Akt, and dual PI3K/mTOR inhibitors have been shown to enhance FOXO3a nuclear localization in breast cancer cells and we have shown here that effective PI3Kα inhibition resulted in FOXO3a nuclear relocation." (PMID 32976773, 2020). "In our previous study, we have confirmed that DPP-4 inhibition induced the EMT through the CXCL12/CXCR4/mTOR axis in breast cancer." (PMID 31991851, 2020). "In breast cancer, overexpression of EVI1 is associated with poor prognosis, stem cell-like and lung-metastatic features, and resistance to allosteric mTOR inhibition." (PMID 32012804, 2020).
breast cancer (continued). "In 2014, Grabinski and Ewald tested the efficacy of ibrutinib (alone or in combination with dactolisib, a PI3K/mTOR inhibitor) on ten different subtypes of breast cancer cells in vitro." (PMID 32532074, 2020). "Hypoxia reduces mTOR activity and induces plasticity and stem-cell-like phenotypes in breast cancer cells." (PMID 32427827, 2020). "FGFR2 amplification has also been reported in metastatic luminal breast cancer and the response to an mTOR inhibitor." (PMID 33364954, 2020). "BHLHE40 promotes PI3K/Akt/mTOR activation in breast cancer, activating tumor progression, but suppresses STAT1 expression in clear cell carcinoma, triggering tumor suppression." (PMID 32577154, 2020). "The miR‐221 suppresses PTEN transcription and activates Akt/mTOR pathway, which in turn enhances breast cancer resistance to adriamycin and promotes cancer development." (PMID 31899608, 2020). "Taken together, our findings demonstrate that microRNA‐221 enhances cancer resistance to adriamycin through suppression of PTEN and activation of Akt/mTOR signaling in breast cancer." (PMID 31899608, 2020). "We have recently shown that a DPP-4 inhibitor accelerated the epithelial mesenchymal transition (EMT) and lung metastasis via the CXCL12/CXCR4/mTOR axis in breast cancer cells." (PMID 31991851, 2020). "A hyperactive PI3K/AKT/mTOR pathway is a characteristic of up to 70% of breast cancers of all molecular breast cancer subtypes, i.e., Luminal A, Luminal B, Her2 (ErbB2)-enriched, as well as basal-like, triple-negative cancers." (PMID 32707827, 2020). "The MTOR signaling pathway is very relevant in breast cancer due to its control of cell growth and metabolic state." (PMID 31945087, 2020). "Everolimus (EVE), an inhibitor of mammalian target of rapamycin (mTOR), is commonly used to treat HT‐resistant breast cancers." (PMID 32810922, 2020). "Another study demonstrated that ITM2A inhibited breast cancer cells growth via enhancing autophagy induction through a mTOR-dependent manner." (PMID 33680917, 2020). "The mammalian target of rapamycin (mTOR) is another signaling pathway closely related to radiation resistance in breast cancer." (PMID 33680952, 2020). "In particular, resveratrol inhibits aerobic glycolysis and PKM2 enzyme in HeLa (human cervical cancer), HepG2 (human liver cancer) and MCF-7 (human breast cancer) cancer cells through the inhibition of mTOR signaling." (PMID 32013090, 2020). "We show for the first time that combining mTOR inhibitors and mitoxantrone has synergistic effects against breast cancer cells in vitro and in vivo." (PMID 33144562, 2020). "Quercetin, naringenin, and isorhamnetin, such as flavonoids, can prevent breast cancer cell migration through inflammatory and apoptotic cell signaling, and quercetin can induce autophagy by inhibiting the Akt-mTOR pathway." (PMID 33062007, 2020). "In the present study, the metabolic properties of breast cancer cell lines were characterised by their protein expression profiles and sensitivity to mTOR and metabolic inhibitors." (PMID 32899149, 2020). "In conclusion, our study showed positive associations between body fatness and mTOR pathway activation, evident by a p-mTOR expression, in breast cancer." (PMID 33024820, 2020). "Above all, we report for the first time that DHW-208 suppressed the growth of human breast cancer cells by inhibiting the PI3K/AKT/mTOR-signaling pathway both in vivo and in vitro." (PMID 32606352, 2020). "Taken together, these findings suggest microRNA‐221 suppresses PTEN transcription and activates Akt/mTOR pathway, which in turn enhances breast cancer resistance to adriamycin and promotes cancer development." (PMID 31899608, 2020). "In the present study, we examined the effects of RE on TN MDA-MB-231 breast cancer cell proliferation, survival/apoptosis, Akt, and mTOR signaling." (PMID 32012648, 2020). "M2 macrophage polarization induces tamoxifen resistance through the activation of the PI3K/Akt/mTOR pathway in breast cancer." (PMID 33376580, 2020).
breast cancer (continued). "Recent evidence suggests that lncRNA NAMPT-AS promoted breast cancer progression and regulated autophagy through the mTOR pathway." (PMID 33614483, 2020). "In conclusion, treatment with sirolimus alone showed significant mammary tumor inhibition which presumably exerts its inhibitory effect through mTOR pathway." (PMID 33112549, 2020). "The PI3K/Akt/mTOR pathway is the most altered pathway in breast cancer, and almost 30% of TNBC cases have PI3K alterations." (PMID 32438621, 2020). "It was suggested that crosstalk between the ER and PI3K/AKT/mTOR signaling pathway exists during breast cancer development." (PMID 33489906, 2020). "This indicates PRR14’s upregulation activates the AKT/mTOR signal pathway and vice versa in breast cancer cells." (PMID 32541902, 2020). "The PAM (phosphoinositide 3 kinase (PI3K)/AKT/mammalian target of rapamycin (mTOR)) pathway is often altered in cancers, being involved in more than 70% of breast cancer cases." (PMID 33375317, 2020). "The PI3K/AKT/mTOR signaling pathway plays an important role in proliferation and survival of breast cancer cells." (PMID 32501811, 2020). "In breast cancer, particularly TNBC and basal-type breast cancer, activation of PI3K/AKT/mTOR-signaling pathway is associated with poor prognosis." (PMID 33194937, 2020). "Oncogenic activation of the mTOR signaling pathway occurs frequently in tumor cells and contributes to the devastating features of cancer, including breast cancer." (PMID 33144562, 2020). "Together, these results suggest that FAK regulation of mTOR signaling pathway contributes to its promotion of tumor growth and metastasis of Wnt1-driven and basal-like breast cancer." (PMID 32493400, 2020). "Metformin indirectly activates AMPK, which then inhibits the mTOR to prevent breast cancer cell proliferation as well as to stop cell growth and pathological cell cycle progression." (PMID 32369516, 2020). "Inducible in vitro deletion of Ctsl in MMTV-PyMT-derived breast cancer cells revealed expansion of the acidic cell compartment, alteration of intracellular amino acid levels, and impaired mTOR signaling." (PMID 32707827, 2020). "Consistent with our finding that RUNX1 bookmarks and regulates rRNA genes, one of the pathways identified is mTOR signaling, a pathway that is required for cell growth and is a therapeutic target in breast cancers." (PMID 32655837, 2020). "The PI3K/Akt/mTOR pathway frequently contributes to breast cancer progression playing a central role in multiple cellular functions and is a key mechanism of resistance to endocrine therapy." (PMID 32770287, 2020). "Everolimus is a mTOR inhibitor which demonstrates clinical activity in several solid tumors, especially in kidney cancer after first line TKI anti VEGF treatment and in breast cancer in association with exemesthane after failure of aroamatase inhibitors." (PMID 32774603, 2020). "The inhibitors of mTOR are widely used in renal cell carcinoma, are safe in brain metastases 109 and are explored in combinations specifically for breast cancer." (PMID 32194848, 2020). "Combined inhibition of PI3K and mTOR was able to overcome resistance to a PI3K inhibitor in an orthotopic model of brain metastasis by HER2-positive breast cancer." (PMID 32399646, 2020). "To further explore the anticancer mechanism of DHW-208, we evaluated the effects of DHW-208 on the PI3K/AKT/mTOR pathway in breast cancer cells using western blot analysis." (PMID 32606352, 2020). "Accordingly, BEZ235, a PI3K and mTOR dual inhibitor has been investigated as a possible treatment in breast cancer by inducing cell cycle arrest and apoptosis 28-31." (PMID 32201525, 2020). "Patients with a tumor of lower grade and smaller size and an earlier stage of breast cancer had higher expression levels of p-mTOR and total phosphoproteins than those with a tumor of higher grade and larger size and a later stage of the disease." (PMID 33024820, 2020).
breast cancer (continued). "Approximately 60% of breast cancer tumors have genetic alterations that activate the PI3K/AKT/mTOR pathway." (PMID 32606352, 2020). "Overall, these results confirmed the inhibitory effect of disulfiram on PI3K/Akt/mTOR signaling pathway, which promoted apoptosis of canine mammary tumor cells." (PMID 33375426, 2020). "have shown that one significant role in breast cancer growth is played by the signaling pathway of mTOR (mammalian target of rapamycin), its downregulation by miR-100 and/or miR-125b enabling cellular death and inhibiting the progression of breast cancer." (PMID 33194751, 2020). "Pharmacological inhibition of FAK and mTOR in human basal-like breast cancer cell lines was also tested." (PMID 32493400, 2020). "Another group revealed that MGN improves sensitivity to DOX via inducing apoptosis and autophagy through AKT/mTOR (mammalian target of rapamycin) and p38 signaling pathways in breast cancer cells." (PMID 33182753, 2020). "A co-amplification of RPS6KB2 and 4EBP1 has been reported, suggesting a synergy between these mTOR targets in breast cancer development and progression." (PMID 32054043, 2020). "First, we used the GEPIA dataset to study the AKT/mTOR pathway members in breast cancer in relation to CHOP or ATF4, both of which are downstream of PERK." (PMID 32508655, 2020). "It was reported that arctigenin (1–200 μM) induced autophagic cell death by inhibiting mTOR activation in ER+ breast cancer (MCF-7) cells." (PMID 32927836, 2020). "Recent studies demonstrate that the PI3K/AKT/mTOR pathway plays an important role in breast cancer cell plasticity." (PMID 32391382, 2020). "In breast cancer, synaptopodin-2 and caveolin-1 have been shown to modulate Akt/mTOR-regulated metastatic progression." (PMID 32615541, 2020). "Inhibition of MAPK pathway and mTOR inhibitor rapamycin both can decrease FASN expression in breast cancer cells." (PMID 33489906, 2020). "Our results indicate that in hypoxic MCF-7 breast cancer cells, HT decreases the expression of HIF-1α, an effect probably linked to its antioxidant action and to the down-regulation of the PI3K/Akt/mTOR pathway." (PMID 32286485, 2020). "The increase in mTOR signaling in cancer cells suggests a potential mechanism by which osteoblasts would regulate breast cancer cell dormancy in the bone." (PMID 32092997, 2020). "Everolimus and temsirolimus have been used as mTOR inhibitors and are approved for the treatment of breast cancer, renal cell carcinoma, and pancreatic neuroendocrine tumors." (PMID 32325639, 2020). "The mechanistic target of rapamycin (mTOR), also known as the mammalian target of rapamycin, is an important target for breast cancer therapy since it is frequently deregulated in breast cancers and plays a critical role in tumorigenesis." (PMID 32054043, 2020). "Breast cancer cell resistance to therapies can result from the activation of PI3K/Akt/mTOR signalling pathway." (PMID 32807213, 2020). "Consistent with the in vitro results, in vivo studies demonstrated that DHW-208 elicits an antitumor effect by inhibiting the PI3K/AKT/mTOR-signaling pathway with a high degree of safety in breast cancer." (PMID 32606352, 2020). "In conclusion, DHW-208 is a dual inhibitor of PI3K and mTOR that can suppress the growth of human breast cancer cells by inhibiting the PI3K/AKT/mTOR-signaling pathway." (PMID 32606352, 2020). "We further demonstrated that mitoxantrone binds to eEF-2K and inhibits its activity, and the combination treatment of mitoxantrone and mTOR inhibitor resulted in significant synergistic cytotoxicity in breast cancer." (PMID 33144562, 2020). "This tumor-based study found positive associations between body fatness and mTOR pathway activation, evident by a p-mTOR expression, in breast cancer." (PMID 33024820, 2020). "For example, blockade of the hyperactivated PI3K/AKT/mTOR pathway by diversified inhibitors should bring up some clinical benefits for breast cancer patients." (PMID 32461963, 2020).
breast cancer (continued). "PI3K/AKT/mTOR is also the most frequently activated signaling pathway in breast cancer and promotes tumor growth and progression." (PMID 32976685, 2020). "We found that p-AMPKα was elevated and p-mTOR was inhibited in aspirin-treated HER-2-positive breast cancer cells." (PMID 32025207, 2020). "Metabolic alterations such as glycolytic hyperactivation, glutamine uptake, lipid metabolism or mTOR activity have been the subject of intensive studies of breast cancer research." (PMID 32899149, 2020). "To explore the mechanisms by which two breast cancer cell lines are more sensitive to carbon ions, we detected the activation level and the total expression level of the Akt/mTOR/p70S6K pathway." (PMID 32239160, 2020). "All of these results suggest that DHW-208 exhibits potential anti-breast cancer effects by inhibiting PI3K/AKT/mTOR pathway with low toxicity in vivo." (PMID 32606352, 2020). "Rapamycin analogs (rapalogs), such as temsirolimus and everolimus, also inhibit the mTOR pathway in renal cancer and breast cancer, among others." (PMID 33194736, 2020). "This is consistent with the previous result that PRR14 activates the Akt/mTOR signaling pathway in breast cancer." (PMID 32541902, 2020). "For example, both lung and breast cancer cell lines and patient tumors eventually evade mTOR inhibition after exposure to the rapamycin derivative RAD001 by increasing AKT phosphorylation through the upregulation of IGF-1 signaling." (PMID 32587773, 2020). "Aberrant activation of the PI3K/AKT/mTOR pathway is an essential step for the growth of human breast cancers." (PMID 32606352, 2020). "In MMTV-erbB-2 transgenic mice which can be induced to develop breast cancer, treatment with buformin deactivated many signaling pathways including mTOR, ER, and β-catenin and eventually significantly impaired the stemness of breast cancer cells." (PMID 33817229, 2020). "The abnormal PI3K/AKT/mTOR pathway is one of the most common genomic abnormalities in breast cancers including triple-negative breast cancer (TNBC), and pharmacologic inhibition of these aberrations has shown activity in TNBC patients." (PMID 33311440, 2020). "This is coincident with increased phosphorylation of downstream mTOR targets both in p66ShcA-S36A-expressing cells in vitro (p4EBP1) and mammary tumors in vivo (p4EBP1 and prS6)." (PMID 31941526, 2020). "Breast cancer mutations also appear in RTKs receptors such as HER 2, and phosphorylation of this receptor leads to PI3K/AKT/mTOR activation." (PMID 33375317, 2020). "levobupivacaine has the potency of reducing breast cancer cell viability, proliferation and also causes cell death by suppressing the PI3K/Akt/mTOR signalling pathway." (PMID 32807213, 2020). "Emerging evidence shows that PI3K/mTOR signaling is related to increasing autophagy and apoptosis and is always activated in cancer including breast cancer." (PMID 33080824, 2020). "Previous clinical data have elucidated the clinical efficacy of the PI3K/AKT/mTOR pathway inhibition in HR+ breast cancer therapy." (PMID 32461963, 2020). "This has made the PI3K/Akt/mTOR signalling pathway an important object of study for understanding the development and progression of breast cancer." (PMID 32807213, 2020). "miR-147 suppresses migration, proliferation, and invasion in breast cancer via the AKT/mTOR signaling pathway." (PMID 32398967, 2020). "In conclusion, this study has demonstrated for the first time that the natural compound AA can effectively inhibit osteoclastogenesis and prevent breast cancer‐induced bone osteolysis through suppression of the PI3K/AKT/mTOR signaling cascade." (PMID 32976685, 2020). "Cardamonin promotes cellular apoptosis through inhibiting NF-κB and mTOR pathways in multiple cancer types including colon cancer, lung cancer and breast cancer." (PMID 33234722, 2020).